ADD2 (adducin 2)
Description:
Membrane-cytoskeleton-associated protein that promotes the assembly of the spectrin-actin network. Binds to the erythrocyte membrane receptor SLC2A1/GLUT1 and may therefore provide a link between the spectrin cytoskeleton to the plasma membrane. Binds to calmodulin. Calmodulin binds preferentially to the beta subunit.
Synonyms: ADDB
Tractability: Antibody: UniProt places it where antibodies can reach, with medium confidence; its Gene Ontology location is reachable by antibodies, with medium confidence. PROTAC: its protein half-life has been measured.
Gene: Protein-coding gene on chromosome 2 (70,607,618 to 70,768,499, reverse strand). Ensembl gene ENSG00000075340.
Subcellular location: Cytoplasm, cytoskeleton; Cell membrane
Subcellular location (Human Protein Atlas): Cytosol; Nucleoplasm; Plasma membrane
Pathways (Reactome):
Transport of small molecules: Miscellaneous transport and binding events
Gene Ontology:
Molecular function: actin binding; actin filament binding; cytoskeletal anchor activity; protein binding; protein dimerization activity; protein heterodimerization activity; protein homodimerization activity; protein kinase binding; spectrin binding; structural constituent of cytoskeleton
Biological process: actin cytoskeleton organization; actin filament bundle assembly; barbed-end actin filament capping; leukocyte migration; leukocyte tethering or rolling; protein-containing complex assembly; regulation of actin filament polymerization; synapse assembly
Cellular component: cytoplasmic vesicle; F-actin capping protein complex; plasma membrane; plasma membrane raft; cytoskeleton; cytosol; postsynaptic density; spectrin-associated cytoskeleton; membrane
Genetic constraint (gnomAD): Loss-of-function variants: 23 observed, 84.03 expected, observed/expected ratio (o/e) 0.27, 90% interval 0.2 to 0.39. The upper end of that interval is the gene's LOEUF score, 0.39, which puts it in group 1 of 6, group 1 being the genes least tolerant of losing a copy. Missense variants: 758 observed, 983.96 expected, observed/expected ratio (o/e) 0.77, 90% interval 0.73 to 0.82. Synonymous variants: 375 observed, 392 expected, observed/expected ratio (o/e) 0.96, 90% interval 0.88 to 1.04.
Homologues: Orthologues: chimpanzee ADD2 (99% identical), macaque ADD2 (99% identical), pig ADD2 (95% identical), rabbit ADD2 (94% identical), mouse Add2 (93% identical), rat Add2 (92% identical), dog ADD2 (92% identical), guinea pig ADD2 (73% identical), tropical clawed frog add2 (71% identical), zebrafish add2 (55% identical), Drosophila melanogaster hts (35% identical), Caenorhabditis elegans add-2 (19% identical). Paralogues in human: ADD3 (54% identical), ADD1 (48% identical).
Diseases named in the same sentence as ADD2 in open-access papers:
ADD2 is named in the same sentence as 15 diseases in open-access papers, as found by Europe PMC text mining. Sharing a sentence is not in itself a finding about the gene and the disease. The quoted sentences say what the papers report.
Hypertension (7 papers, 2007 to 2025). The presence of chronic increased pressure in the systemic arterial system. "However, researchers have found that Gly460Trp polymorphism in interaction with C1797T polymorphism of ADD2 increases the risk of hypertension in all women (adjusted relative risk, RR = 2.35, P=0.01) and postmenopausal subjects (RR = 2.92, P=0.03), but not in men." (PMID 34055401, 2021). "We suspected that ADD2 could be associated with differences in response to different antihypertensives because adducins have been proposed to regulate renal tubular transport of Na+ reabsorption and the development of hypertension." (PMID 17854487, 2007). "Mutations in the genes ADD1, ADD2, and ADD3 have been linked to hypertension, neurodevelopmental disorders, and cancer." (PMID 40869965, 2025). "Surprisingly, we found only one gene, coding for adducin 2-beta, involved in the development of hypertension in the brain." (PMID 22272763, 2012). "We also investigated adducin, the heterodimeric cytoskeleton protein whose three subunits are encoded by ADD1, ADD2 (protein accession number C9J080, FC = 0.00), and ADD3, respectively; the role of adducin in hypertension and its downregulation-related disorders have been reported." (PMID 36002804, 2022).
adenoma (1 paper, 2016). A neoplasm arising from the epithelium. "Comparing adenoma + CRC with normal tissues, ADD2 and AKR1B1 have higher AUCs than SEPT9." (PMID 27493446, 2016).
atrial fibrillation (1 paper, 2025). A disorder characterized by an electrocardiographic finding of a supraventricular arrhythmia characterized by the replacement of consistent P waves by rapid oscillations or fibrillatory waves that vary in size, shape and timing and are accompanied by an irregular ventricular response. "At the RNA level, RT-qPCR confirmed expression changes in CACNG4 (cardiac arrythmia), GJA5 (atrial fibrillation), THBS2 (angiogenesis inhibitor), ADD2 (membrane skeletal protein, synaptic plasticity), and HAND2 (neurogenesis)." (PMID 39508990, 2025).
breast carcinoma (1 paper, 2024). "ULK1/2 inhibits the actin assembly and hinders breast cancer cell contraction and migration, Selective splicing of genes in the intronic protein family, including ADD2, leads to alterations in cellular function during pathogenesis are associated with cancer." (PMID 39698112, 2024).
glioma (1 paper, 2024). A benign or malignant brain and spinal cord tumor that arises from glial cells (astrocytes, oligodendrocytes, ependymal cells). "Furthermore, survival analysis revealed that patients with glioma with high expression of ADD2, CTC1, SRCIN1, VPS4A, ULK2, excluding RORA, had a longer overall survival than those with low expression." (PMID 39698112, 2024). "Similarly, disease-free survival was found to be longer in patients with glioma with high expression of ADD2, CTC1, SRCIN1, RORA, VPS4A, and ULK2 than in those with low expression." (PMID 39698112, 2024). "We found significant differences in the expression levels of ADD2, CTC1, SRCIN1, RORA, and ULK2 genes in gliomas of different grades, excluding VPS4A." (PMID 39698112, 2024).
cancer (5 papers, 2012 to 2025). A tumor composed of atypical neoplastic, often pleomorphic cells that invade other tissues. "ADD2 encodes a cytoskeletal protein that interacts with FYN, a tyrosine kinase promoting cancer cell migration." (PMID 23046790, 2012). "It was found that eight proteins (ADD2, DEF6, DOK3, ENO2, FMNL1, MICALL2, PARVG, and PSTPIP1) in KIRC cancer were more highly expressed in tumor tissues (100%), compared with normal tissues." (PMID 36428765, 2022). "Cancer and organismal injuries were the top two diseases and function categories that were predicted to increase, along with neurological (HAND2), hepatic system (APOE, CACNG4, CAMK2B), respiratory system (WNT16), and skeletal muscle developmental disorders (ADD2, HAND2)." (PMID 39508990, 2025).
tumor (4 papers, 2019 to 2025). "cg21384971 is associated with less expression of the COPZ2 gene, which has been studied as a therapeutic opportunity for proliferation-independent selective killing of tumour cells. cg11220663 is associated with less expression of the ADD2 gene, also known as beta-adducin." (PMID 31142478, 2019). "Similarly, while ADD2 gene mutations have been linked to tumor progression, it remains unclear whether they serve as primary oncogenic drivers or act indirectly by disrupting cytoskeletal dynamics." (PMID 40869965, 2025).
neurologic disease (1 paper, 2015). "SAFB1 mediated isoform-specific changes in ANK3, ANKS1B, SAP97 (DLG1), ADD2, KIF16B, and ELK3, as well as in genes linked to the cytoskeleton and/or synaptic function and the aetiology of neurologic disease." (PMID 26694817, 2015).
ADD2 also shares sentences with these, for which no sentence is quoted: cardiac hypertrophy (1 paper); Cognitive impairment (1); endometrial cancer (1); epilepsy (1); malaria (1); neurodevelopmental disorder (1); systemic lupus erythematosus (1).